IFI6 (interferon alpha inducible protein 6)
Diseases named in the same sentence as IFI6 in open-access papers (continued):
Sharing a sentence is not in itself a finding about the gene and the disease.
melanoma (continued). "In addition to identifying the role for IFI6 in the regulation of melanoma development and tumor growth, we also discovered a previously undocumented role for IFI6 in the regulation of DNA replication." (PMID 27608486, 2016). "Therefore, we asked if IFI6 knockdown results in dysregulated DNA replication-induced cellular senescence, which may consequentially inhibit melanoma growth." (PMID 27608486, 2016). "Our previous study also showed that IFI6 is a target of NRAS and promotes tumor growth by suppressing DNA replication stress in melanoma cells." (PMID 36338541, 2022). "For instance, interferon alpha-inducible protein 6 (IFI6) is reportedly necessary for oncogenic NRAS-induced transformation and melanoma growth." (PMID 34650128, 2021). "Taken together, our results identify a new role for IFI6 in E2F2-mediated regulation of DNA replication and melanoma development and growth." (PMID 27608486, 2016). "Further studies revealed that the introduction of NRASQ61K in primary human melanocytes increased IFI6 expression and downregulated E2F2 and several E2F2 target genes, similar to melanoma cells." (PMID 27608486, 2016). "Collectively, we demonstrate that IFI6, via E2F2 regulates DNA replication and melanoma development and growth, and this pathway can be pharmacologically targeted to inhibit NRAS-mutant melanoma." (PMID 27608486, 2016). "Pharmacological inhibition of IFI6 expression by the MEK inhibitor trametinib, when combined with DNA replication stress-inducing drugs, blocked NRAS-mutant melanoma growth." (PMID 27608486, 2016). "In this report, we show that IFI6 regulates oncogenic NRAS-induced melanocyte transformation and NRAS-mutant melanoma tumor growth." (PMID 27608486, 2016). "Collectively, these results demonstrate that IFI6 is necessary for NRASQ61K-induced transformation and NRAS-mutant melanoma growth." (PMID 27608486, 2016). "First, our results demonstrate that IFI6 expression is activated by oncogenic NRAS, which is necessary for oncogenic NRAS-induced transformation and melanoma tumor growth." (PMID 27608486, 2016). "To determine this, we simultaneously knocked down the expression of E2F2 and IFI6 using shRNA and observed a significant rescue of the NRAS-mutant melanoma cell's ability to form colonies in soft agar and tumors in mice." (PMID 27608486, 2016). "Here, we show that interferon alpha-inducible protein 6 (IFI6) is necessary for NRASQ61K-induced transformation and melanoma growth." (PMID 27608486, 2016). "In addition, treatment with the MEK inhibitor trametinib, which reduces IFI6 expression, when combined with drugs that induce DNA replication stress, potently inhibited NRAS-mutant melanoma tumor growth in cell culture and in mice." (PMID 27608486, 2016). "Finally, we analyzed the expression of IFI6 and key MAPK transcriptional targets in 20 patient-derived melanoma samples." (PMID 27608486, 2016). "Thus, the ability of IFI6 to regulate DNA replication stress originates in its ability to repress E2F2 and its target genes specifically in the context of NRAS-mutant melanoma." (PMID 27608486, 2016). "Because we had observed that the MAPK pathway regulates IFI6, we tested whether pharmacological MEK inhibitors could be combined with DNA replication stress-inducing drugs to treat NRAS-mutant melanoma." (PMID 27608486, 2016). "However, we also identified three interferon-stimulated genes (ISGs)—IFI6, IFI27, and MX1—that have not been previously implicated in oncogenic NRAS-induced transformation and melanoma tumor growth." (PMID 27608486, 2016). "Notably, knockdown of IFI6 in BRAF-mutant, NF1-deficient, or triple wild-type melanoma did not alter the expression of E2F2 or its target genes." (PMID 27608486, 2016).
esophageal squamous cell carcinoma (6 papers, 2020 to 2025). Esophageal squamous cell carcinoma (ESCC) is a type of esophageal carcinoma (EC) that can affect any part of the esophagus, but is usually located in the upper or middle third. "IFI6 depletion has been reported to suppress proliferation and induce apoptosis by increasing ROS accumulation in esophageal squamous cell carcinoma." (PMID 39988631, 2025). "IFI6 depletion inhibits esophageal squamous cell carcinoma progression." (PMID 35267998, 2022). "Other studies have found that the expression of IFI6 is significantly elevated in esophageal squamous cell carcinoma (ESCC) patients and ESCC cell lines cultured in vitro." (PMID 38033564, 2023).
colorectal cancer (4 papers, 2015 to 2025). A primary or metastatic malignant neoplasm that affects the colon or rectum. "ELF3 overexpression is involved in the metastasis process in non-small cell lung cancer and its expression can be a useful biomarker of lymph node metastasis in colorectal cancer, while IFI6 promotes metastasis in breast cancer cells." (PMID 30939818, 2019). "The regulation of JMJD2B in a HIF-1α-dependent manner during hypoxia increases the invasiveness of colorectal cancer cells by reducing the levels of the repressive mark H3K9me3 in genes like ELF3 (E74-like ETS transcription factor 3) and IFI6 (Interferon Alpha Inducible Protein 6)." (PMID 30939818, 2019).
Hepatitis C (4 papers, 2020 to 2024). "IFI6 is implicated in apoptosis regulation and exhibits a role in hepatitis C virus infection." (PMID 32603365, 2020). "SARS-CoV-2 infection promotes IFI6 expression, but an inhibitory effect in hepatitis C virus infection and Ebola virus replication has also been suggested according to the expression of this gene." (PMID 38731851, 2024). "An intriguing discovery in our investigation lies in the linkage uncovered using KEGG analysis between IFI6 and its genes that positively correlate with the Hepatitis C pathway." (PMID 38473938, 2024).
hepatoma (4 papers, 2015 to 2024). "IFI6 was one of a number of ISGs shown to inhibit yellow fever virus (YFV) infection in STAT1-deficient human (STAT1−/−) fibroblasts or in human hepatoma cells." (PMID 25757571, 2015). "Recent studies have found that the human IFI6 protein is located in the endoplasmic reticulum in human hepatoma cells and blocks yellow fever virus replication by blocking the invagination of the endoplasmic reticulum membrane." (PMID 38033564, 2023). "We examined the effect of interferon-α inducible protein 6 (IFI6) against HCV infection in human hepatoma cells." (PMID 25757571, 2015). "The IFI6 was highly induced by the stimulation of IFN-α in hepatoma cells." (PMID 33868257, 2021). "In examining intrahepatic IFN-stimulated genes and evaluating the functional role of IFI6 in the context of HBV immune response, we determined the expression level of IFI6 by inducing hepatoma cell lines with IFN-α that significantly induces IFI6 expression." (PMID 33868257, 2021).
influenza (4 papers, 2018 to 2024). An acute viral infection of the respiratory tract, occurring in isolated cases, in epidemics, or in pandemics; it is caused by serologically different strains of viruses (influenzaviruses) designated A, B, and C, has a 3-day incubation period, and usually lasts for 3 to 10 days. "Second, influenza infection upregulated IFI6 in BAL cells and decreased their susceptibility to virus replication in vitro." (PMID 39024231, 2024). "According to recent publications, in 2009, researchers from Duke University confirmed that IFI6 was shown to be down-regulated during the pathogenesis of influenza and other symptomatic respiratory viral infections." (PMID 33505977, 2020). "In our study, we observed reduced GFP expression in VSVΔG-GFP infected BAL cells from pH1N1 infected pigs compared to those from control pigs, confirming a persistent antiviral state following influenza infection and suggesting mediation by differentially expressed gene IFI6." (PMID 39024231, 2024). "In influenza patients, the interferon pathway-related genes IFI44, IFI6, IFIH1, STAT1, and GBP1 also showed overexpression, while no obvious interferon transcriptional signature was observed in AECOPD and CAP." (PMID 36059536, 2022).
ovarian carcinoma (4 papers, 2016 to 2023). A malignant neoplasm originating from the surface ovarian epithelium. "C0 and C4 did not express ACTA2 or VIM, the marker genes for cancer-associated fibroblasts (CAFs), and expressed IFI6, which is associated with a malignant subpopulation in ovarian cancer, at a comparable level to other tumor clusters." (PMID 35892844, 2022). "In ovarian cancer (OC), it was found that interferon-α inducible protein 6 (IFI6) was found to promote the proliferation of OC cells by activating the NF-κB pathway and induces cisplatin resistance." (PMID 37990103, 2023). "In an ovarian cancer research, the overexpression of IFI6 could facilitate the multiplication of tumor cells and mediate their chemoresistance." (PMID 37670388, 2023).
tongue squamous cell carcinoma (4 papers, 2015 to 2024). A squamous cell carcinoma that arises from the tongue. "Here we discovered that ATF3 plays an anti-tumor role in tongue squamous cell carcinoma (TSCC) cells through the transcriptional suppression of its new downstream targets interferon alpha inducible proteins 6 (IFI6) and 27 (IFI27)." (PMID 33539340, 2021). "The most differentially upregulated genes were IFI6 and IFI27, which play an important role in apoptosis and may promote the growth and migration of tongue squamous cell carcinoma." (PMID 38254880, 2024).
autoimmune disease (3 papers, 2023 to 2024). A disorder resulting from loss of function or tissue destruction of an organ or multiple organs, arising from humoral or cellular immune responses of the individual to their own tissue constituents. "In recent years, several studies have shown that IFI6 is associated with a variety of malignant diseases; notably, IFI6 is highly expressed in various malignant tumors, virus-related diseases and autoimmune diseases." (PMID 38033564, 2023). "To date, research on IFI6 has mainly focused on human malignant tumors, virus-related diseases and autoimmune diseases." (PMID 38033564, 2023). "In SIgAD patients with concomitant autoimmune diseases, decreased expression levels of genes related to the type I interferon (IFN) pathway, including IFIT1, MX1, IFI6, and IFI44L, were observed." (PMID 38474381, 2024).
lung adenocarcinoma (3 papers, 2022 to 2025). A carcinoma that arises from the lung and is characterized by the presence of malignant glandular epithelial cells. "We found that the overexpression of IFI6 under the influence of the AHSA1-HSP90AA1 complex significantly enhances Osimertinib resistance in EGFR-mutated lung adenocarcinoma cells." (PMID 40234395, 2025). "Regarding mechanisms, the AHSA1-HSP90AA1 complex stabilizes IFI6 and TGFB1 to enhance cell survival and Osimertinib resistance in EGFR mutant lung adenocarcinoma." (PMID 40234395, 2025). "The IFI6 protein plays a central role in resistance to apoptosis in various cancer types, and MX1 protein levels are increased in lung adenocarcinoma." (PMID 35354498, 2022).
systemic lupus erythematosus (3 papers, 2020 to 2022). An autoimmune multi-organ disease typically associated with vasculopathy and autoantibody production. "One example is systemic lupus erythematosus, a disorder associated with skin and joint inflammation, accelerated atherosclerosis, and upregulation of genes such as IFI6 and OASL." (PMID 31539532, 2020). "Furthermore, the expression of IFI6 is elevated in the blood or platelet samples of patients with systemic lupus erythematosus (SLE), rheumatoid arthritis (RA), primary antiphospholipid syndrome, and MS." (PMID 35609018, 2022).
ZIKV infection (3 papers, 2018 to 2024). "RNA-seq analysis of HT-29 cells revealed that ZIKV infection caused the upregulation of IFNB and several innate immune response genes, including FAM60A, IFI6, DDX58, OAS1, MX1, and IP-10." (PMID 30333476, 2018). "In contrast to Zika virus infection, exogenous IFNɛ strongly induced ISG15, OAS1, IFIT1, and IFI6 within 12 hours post-treatment." (PMID 39621805, 2024). "Key ISGs that protect against ZIKV infection (Viperin, ISG15, IFITM1, IFI6) were significantly upregulated compared to control in all three treatments." (PMID 36897927, 2023).
asthma (2 papers, 2012 to 2022). "As RSV leads to the inflammation of the epithelium in affected patients and as a previous GWAS demonstrated that genes implicated in the epithelial function are strongly associated with asthma, the IFI6 gene could play a role in asthma through the modulation of the epithelium structure." (PMID 23148572, 2012). "We showed that four genes are genetically associated with asthma or asthma-related phenotypes (the AGC1 gene associated with atopy and atopic asthma, the IFI6, ADRA2A and ADH1B genes associated with asthma)." (PMID 23148572, 2012). "The rs11630178 in the AGC1 gene is associated with atopy (p=0.0003) and atopic asthma (p=0.0001), the rs1247653 located in the IFI6 gene (p=0.019), the rs1119529 in the ADRA2A gene (p=0.009) and the rs13103321 in the ADH1B gene (p=0.002), are associated with asthma." (PMID 23148572, 2012).
colon cancer (2 papers, 2017 to 2021). "Regarding colon cancer network, genes including NME2, ATP1A1, CD24 and IFI6 showed the most connectivity." (PMID 29118934, 2017).
Flavivirus Infections (2 papers, 2020 to 2021). Infections with viruses of the genus FLAVIVIRUS, family FLAVIVIRIDAE. "IFI6, an additional ISG that was recently shown to protect cells from Flavivirus infection, was also shown to be upregulated." (PMID 32127025, 2020).
leukemia (2 papers, 2023). A malignant (clonal) hematologic disorder, involving hematopoietic stem cells and characterized by the presence of primitive or atypical myeloid or lymphoid cells in the bone marrow and the blood. "Next, we aimed to explore the underlying mechanism by which IFI6 promotes leukemia cell proliferation." (PMID 37670388, 2023). "We elucidated IFI6's positive role in the leukemia cell multiplication, and explored the underlying molecular mechanisms." (PMID 37670388, 2023). "To further unravel IFI6's role in the molecular biological characteristics of leukemia cells, we co-cultured MSCs from EV group and LV-IFI6 group with RS4;11 cells for 72 h, respectively, and then collected leukemia cells for transcriptome sequencing analysis." (PMID 37670388, 2023). "Further, interferon alpha-inducible protein 6 (IFI6), as a gene activated by interferon, was highly expressed in leukemia niche MSCs." (PMID 37670388, 2023). "In the following experiments, we further applied mice with NOD/SCID to investigate IFI6's role in the growth and proliferation of leukemia cells." (PMID 37670388, 2023). "In this study, AMD3100 also effectively attenuate the pro-proliferative effect of IFI6 on leukemia cells." (PMID 37670388, 2023). "As suggested by further RNA sequencing analysis, the high IFI6 level in MSCs somewhat influenced the gene expression profile and biological functions of leukemia cells." (PMID 37670388, 2023). "Finally, we also found in this work that the increased expression of IFI6 in MSCs had some effects on the gene expression profile and biological functions of leukemia cells through RNA sequencing." (PMID 37670388, 2023). "As implied by these findings, the elevated IFI6 in MSCs might promote the proliferation of leukemia cells." (PMID 37670388, 2023). "We speculated whether the increased expression of IFI6 in MSCs could facilitate the leukemia cell multiplication by stimulating the SDF-1/CXCR4 axis." (PMID 37670388, 2023). "Taken together, we speculated that the IFI6 level elevation in the co-cultured MSCs produced a certain effect on the gene expression profile and proliferation of leukemia cells." (PMID 37670388, 2023). "As implied by these findings, the pro-proliferative function of IFI6 for leukemia cells might be exerted through the SDF-1/CXCR4/ERK signal stimulation." (PMID 37670388, 2023). "Mechanistically, IFI6 might promote leukemia cell proliferation by stimulating SDF-1/CXCR4 axis, which leads to the initiation of downstream ERK signaling pathway." (PMID 37670388, 2023). "Targeting IFI6 or related signaling pathways might be an important measure to reduce the leukemia cell proliferation." (PMID 37670388, 2023). "By functional testing, results showed that the high expression of IFI6 in MSCs had a slight effect on the changes of sensitivity of leukemic cells to vincristine, migration and invasiveness of leukemia cells, but exerted a pro-proliferative effect on the leukemia cells." (PMID 37670388, 2023). "These datas suggested that high expression of IFI6 in MSCs might promote the leukemia cell growth and multiplication in vivo." (PMID 37670388, 2023). "And the high expression of IFI6 in leukemia niche is probably critical to the leukemia proliferation promotion by MSCs, targeting IFI6 or related signaling pathways might be an important measure to reduce leukemia cell proliferation." (PMID 37670388, 2023). "In the present work, we found that IFI6 might be an important component in the B-ALL microenvironment that promotes the proliferation of leukemia cells." (PMID 37670388, 2023). "Based on this result, the level of CXCR4, the SDF-1 receptor, in leukemia cells was further examined, finding that in the co-culture system, up-regulation of IFI6 could significantly increase the leukemia cell level of CXCR4, while down-regulation of IFI6 yielded the opposite results." (PMID 37670388, 2023).
leukemia (continued). "In the present work, IFI6 was found capable of initiating the ERK signaling pathway via the SDF-1/CXCR4 axis, thereby facilitating the leukemia cell multiplication." (PMID 37670388, 2023). "To further describe how DEGs in MSCs affect the leukemia cells, in this study, we screened IFI6, an interferon-stimulated gene, which though has not been explored in B-ALL." (PMID 37670388, 2023).